CGA (glycoprotein hormones, alpha polypeptide)
Diseases named in the same sentence as CGA in open-access papers (continued):
Sharing a sentence is not in itself a finding about the gene and the disease.
Cushing syndrome (2 papers, 2015 to 2025). Cushing's syndrome (CS) encompasses a group of hormonal disorders caused by prolonged and high exposure levels to glucocorticoids that can be of either endogenous (adrenal cortex production) or exogenous (iatrogenic) origin. "Serum neuroendocrine biomarkers can rarely help in diagnostic process, only a slight increase in CgA and NSE was reported in seven cases, and in one case an ectopic Cushing syndrome was described." (PMID 40542625, 2025). "Post-operative clinical and biochemical resolution of Cushing’s syndrome was followed by normalization of both CgA and 5HIAA, which were maintained at the 6 month follow-up." (PMID 26610855, 2015).
dyspepsia (2 papers, 2024 to 2026). An uncomfortable, often painful feeling in the stomach, resulting from impaired digestion. "This case presents a 69-year-old female who presented with dyspepsia, and on subsequent endoscopic evaluation, she was found to have AMAG in the context of elevated levels of serum chromogranin A (CgA) and gastrin, suggestive of a GNET." (PMID 41728546, 2026).
edema (2 papers, 2015 to 2025). An abnormal accumulation of fluid beneath the skin, or in one or more cavities of the body. "For example, it is possible that CgA/VS-1-dependent changes in the homeostatic mechanisms related to endothelial barrier may have a role in hydrops and, consequently, in vertigo clustering attack." (PMID 25983374, 2015).
endometriosis (2 papers, 2025 to 2026). The growth of functional endometrial tissue in anatomic sites outside the uterine body. "Receiver operating characteristic (ROC) analysis further confirmed that endometriosis is associated with increased circulating CgA, catestatin, and pancreastatin levels, suggesting that they may be considered markers of endometriosis." (PMID 41753254, 2026). "Since endometriosis may be considered an autoinflammatory disorder, this study aimed to evaluate serum and peritoneal fluid concentrations of CgA and its derivatives, catestatin and pancreastatin, and to correlate these levels with disease severity." (PMID 41753254, 2026). "Elevations of CgA have been reported in gynecologic malignancy (e.g., uterine corpus large-cell neuroendocrine carcinoma and ovarian carcinoma) and may even occur in benign conditions (leiomyoma/endometriosis)." (PMID 41480370, 2025).
frontotemporal dementia (2 papers, 2020 to 2021). Frontotemporal dementia (FTD) comprises a group of neurodegenerative disorders, characterized by progressive changes in behavior, executive dysfunction and language impairment, as a result of degeneration of the medial prefrontal and frontoinsular cortices. "Furthermore, the connection of secretory proteins with neurodegeneration, but not with amyloid plaque pathology, is consistent with recent proteomic studies in non-AD neurodegenerative diseases, such as frontotemporal dementia, where a decline of CgA, VGF and CysC occurs in the CSF of patients." (PMID 34565482, 2021).
goblet cell adenocarcinoma (2 papers, 2014 to 2023). "Immunohistochemical staining of signet ring-like cells in goblet cell adenocarcinoma was positive for CgA, SyN, and CD56." (PMID 37543827, 2023). "In all cases of goblet cell carcinoid/MANEC, CgA and synaptophysin were present only in scattered neoplastic cells." (PMID 24695372, 2014).
Hypoglycemia (2 papers, 2019 to 2025). A decreased concentration of glucose in the blood. "In dogs, plasma levels of CgA increased after physiological stress (insulin-induced hypoglycemia); and increases in salivary CgA were found after psychogenic stress in humans (arithmetic task), pigs (immobilization with nose snare), and cows (social isolation)." (PMID 31527914, 2019).
Insulin resistance (2 papers, 2025). Increased resistance towards insulin, that is, diminished effectiveness of insulin in reducing blood glucose levels. "To dissect the contributions of CgA-derived peptides to peripheral insulin resistance, we supplemented CgA-KO mice with intraperitoneal PST, CST, or a combination of both peptides at equimolar concentrations for one month." (PMID 41298823, 2025). "These pleiotropic, sometimes bidirectional actions mirror the heterogeneity of PCOS pathophysiology and offer plausible biological routes through which CgA could correlate with both insulin resistance and low-grade inflammation in clinical cohorts." (PMID 41480370, 2025). "Peptide supplementation experiments in CgA-KO mice revealed that CST suppressed gluconeogenesis and enhanced glucagon regulation, whereas PST promoted insulin resistance and glucose production." (PMID 41298823, 2025).
intestinal obstruction (2 papers, 2021 to 2023). Blockage of the normal flow of the intestinal contents within the bowel. "For example, in emergency surgeries due to intestinal obstruction or CgA was not available for statistical analysis (missing n = 11)." (PMID 37077861, 2023).
kidney infections (2 papers, 2013 to 2024). "Extensive antimicrobial resistance of uropathogenic E. coli and CgA isolates necessitate the adoption of alternate strategies to circumvent antibiotic resistance while treating cystitis and pyelonephritis associated with such isolates." (PMID 38454332, 2024). "A similar investigation of 25 CgA isolates from poultry meat, chickens, and humans showed that all CgA strains from meat or food animals caused lower UTIs, and all but one of the isolates produced kidney infections." (PMID 23508293, 2013). "Our research findings not only validate the significant occurrence of multidrug-resistant clonal group A E. coli (CgA) in premenopausal Pakistani women suffering from cystitis and pyelonephritis but also reveal the presence of genes associated withvirulence, and drug efflux pumps." (PMID 38454332, 2024).
memory impairment (2 papers, 2024 to 2025). "In the probe trial, PS19 mice took longer time and fewer entries to enter the target quadrant than WT mice, indicative of memory impairment, whereas CgA-KO/PS19 mice performed indistinguishably from the WT." (PMID 40393970, 2025). "The average latency in the probe trial for hTau mice was significantly longer than WT mice, indicative of memory impairment, whereas CgA-KO/hTau mice performed indistinguishably from the WT, spending significantly less time and more entries to the target zone during the probe trial." (PMID 39149499, 2024).
metastatic carcinoma (2 papers, 2013 to 2014). A carcinoma which has spread from the original site of growth to another anatomic site. "In the tumour finally diagnosed as metastatic carcinoma, immunodetection of CgA was negative and synaptophysin was detected small number of tumour cells only." (PMID 24695372, 2014).
migraine (2 papers, 2015 to 2022). "The present study could contribute to add elements about a central effect of CGA, and CGRP mABs in general, in migraine patients." (PMID 35484504, 2022).
pancreatic ductal adenocarcinoma (2 papers, 2020 to 2022). An infiltrating adenocarcinoma that arises from the epithelial cells of the pancreas. "Plasma levels of CgA and fragments in patients with pancreatic ductal adenocarcinoma (PDAC) and in healthy subjects." (PMID 33425767, 2020). "The extent and the role of CgA fragmentation were investigated in patients with locally advanced or metastatic pancreatic ductal adenocarcinoma (PDAC, n=172)." (PMID 33425767, 2020). "Experimental evidence, obtained using various pre-clinical models of pancreatic ductal adenocarcinoma, suggests that the plasminogen activator/plasmin system has a role in CgA processing in this case, and that CgA cleavage has a functional role of in the regulation of tumor vascular biology." (PMID 36559048, 2022).
periodontal disease (2 papers, 2018 to 2024). "CgA and AA have been implicated in altering proinflammatory and anti-inflammatory cytokine production and have been shown to affect periodontal disease activity." (PMID 30043934, 2018). "Furthermore, it has been declared that CgA is also associated with periodontal disease." (PMID 30043934, 2018). "For this reason, CgA fragments are likely to be produced locally by human PMNs in periodontal disease." (PMID 30043934, 2018).
pituitary tumor (2 papers, 2019). A benign or malignant neoplasm affecting the pituitary gland. "Elevated CgA levels have also been associated with a plethora of endocrine diseases, including neoplastic conditions, such as hyperthyroidism and hyperparathyroidism, as well as different endocrine tumors, such as pheochromocytoma, pituitary tumors, and medullary thyroid carcinoma." (PMID 31382663, 2019). "Therefore, the lower plasma EM66 levels in patients with gonadotroph tumor could be related to a lower proteolytic activity of PC1/3 and PC2 in the tumors as already suggested for CgA processing in pituitary tumors." (PMID 30853937, 2019).
renal dysfunction (2 papers, 2020 to 2023). "However, plasma CgA concentrations may fluctuate with proton pump inhibitor and renal dysfunction." (PMID 38082268, 2023).
sarcoma (2 papers, 2021 to 2022). A usually aggressive malignant neoplasm of the soft tissue or bone. "Besides neural cell adhesion molecules (CD56), other neuroendocrine markers synaptophysin (Syn), neuron-specific enolase (NSE), and chromogranin A (CgA) are often used in differential diagnosis of sarcoma." (PMID 35372059, 2022).
small intestinal NETs (2 papers, 2020 to 2021). "In GEP-NETs, high serum CgA levels correlated with shorter survival and liver metastasis as reported in small intestinal NETs accompanied by up to 200 times above normal levels and up to 150 times higher MEN1 cases." (PMID 33485291, 2021). "In GEP-NETs, high serum CgA levels correlate with shorter survival and liver metastasis as reported in small intestinal NETs with up to 200 times above normal levels and in MEN-1 cases up to 150 times higher levels." (PMID 32020844, 2020).
systemic inflammatory response syndrome (2 papers, 2014 to 2022). SIRS is a serious condition related to systemic inflammation, organ dysfunction, and organ failure. "High levels of CgA and VS-1 have been also described in fatal cases of systemic inflammatory response syndrome." (PMID 35468164, 2022).
Zollinger-Ellison syndrome (2 papers, 2017 to 2021). Zollinger-Ellison syndrome (ZES) is characterized by severe peptic disease (ulcers/esophageal disease) caused by hypergastrinemia secondary to a gastrinoma resulting in increased gastric acid secretion. "In Pan-NETs, both functioning and non-functioning tumors showed serum CgA levels at 60 ~ 80 times the normal upper levels, particularly in Zollinger-Ellison syndrome in MEN1 cases with serum CgA levels being 80 ~ 100 times higher than the normal upper levels." (PMID 33485291, 2021).
adrenal tumor (1 paper, 2014). "Immunohistochemistry analysis of the adrenal tumor was strongly positive for CgA, synaptophysin and VIP." (PMID 25081061, 2014).
ameloblastoma (1 paper, 2025). The most common odontogenic tumor, arising from the epithelial component of the embryonic tooth and usually affecting the molar-ramus region of the mandible or maxilla. "Immunohistochemically, ameloblastomas often express CD56; however, novel neuroendocrine markers such as synaptophysin (SYP), insulinoma-associated protein 1 (INSM1), and chromogranin A (CgA) remain unexplored." (PMID 39937015, 2025). "We analyzed 36 ameloblastoma specimens for CD56, SYP, CgA, and clusterin (CLU) and examined limited samples for INSM1 expression by performing immunohistochemistry, transmission electron microscopy, and reverse transcriptase-polymerase chain reaction." (PMID 39937015, 2025). "Therefore, first of all, we investigated the nature of ameloblastomas using the classic and revised neuroendocrine markers, CD56, SYP, CgA, and INSM1, as well as the correlation between CLU and the expression of neuroendocrine markers." (PMID 39937015, 2025). "This study is the first to suggest neuroendocrine differentiation in a small subset of ameloblastomas, characterized by SYP positivity and CgA negativity, along with INSM1 immunoexpression, in line with the recent understanding of neuroendocrine characteristics in the WHO classification." (PMID 39937015, 2025). "We examined neuroendocrine markers, including CD56, SYP, and CgA, in 36 ameloblastomas and identified five specimens that exhibited the immunoexpression of CD56 and SYP, suggesting neuroendocrine differentiation in ameloblastomas." (PMID 39937015, 2025). "SYP-positive and CgA-negative phenotypes may characterize neuroendocrine differentiation in ameloblastoma." (PMID 39937015, 2025).
amyotrophic lateral sclerosis (1 paper, 2019). Amyotrophic lateral sclerosis (ALS) is a neurodegenerative disease characterized by progressive muscular paralysis reflecting degeneration of motor neurons in the primary motor cortex, corticospinal tracts, brainstem and spinal cord. "Several studies connected CgA to pathological features of Amyotrophic lateral sclerosis (ALS)." (PMID 31263455, 2019).
anemia (1 paper, 2020). A reduction in the number of red blood cells, the amount of hemoglobin, and/or the volume of packed red blood cells. "Based on our pilot analysis, PIT values and their anemia-corrected variants appeared to be higher in the CgA+ group (Figure A2) even though aggregation inhibition therapy was more common in the CgA+ group (CgA−: 2 of the 15 patients (13%), CgA+: 5 of the 8 patients (62.5%), p = 0.0257)." (PMID 33383764, 2020).
Anorexia (1 paper, 2021). Lack of desire to eat (loss of appetite). "In addition, bloating correlated with CgA (r = 0.85, P = 0.03), anorexia correlated with each of secretin (r = −0.91, P = 0.01) and GIP (r = −0.95, P=0.003), and nausea correlated with each of CCK (r= –0.89, P=0.01) and GIP (r= –0.95, P=0.003) in the idiopathic IBS subgroup." (PMID 34055657, 2021).
asthma (1 paper, 2021). "One patient (pt.2) had a mildly elevated chromogranin A (CgA) level of 111 ng/mL (normal 0–95 ng/mL), but also suffered from asthma and took a serotonin specific reuptake inhibitor, which are both factors that can lead to an elevation of CgA." (PMID 33377995, 2021).
autoimmune disease (1 paper, 2025). A disorder resulting from loss of function or tissue destruction of an organ or multiple organs, arising from humoral or cellular immune responses of the individual to their own tissue constituents. "Considering that CgA and its cleavage products were found to be associated with various pathological conditions (such as cancer, autoimmune diseases, and cardiovascular disorders), the present review aims to summarize their putative role in infection, inflammation, and inflammatory diseases." (PMID 40370467, 2025).
Bladder Paraganglioma (1 paper, 2023). A benign or malignant extra-adrenal sympathetic paraganglioma arising from the urinary bladder. "The result of postoperative pathology was immediate-risk functional bladder paraganglioma (T2N0M0, Stage II) concomitant with urothelial papilloma, and the immunohistochemistry results of PPGL were positive for Ki-67 (15%), SDHB, CgA, and SSTR2." (PMID 36741690, 2023).
blood pressure (1 paper, 2022). "Strikingly, the high blood pressure in young CgA-KO mice was spontaneously reversed in 2-yr-old CgA-KO mice." (PMID 36440192, 2022).
bone fracture (1 paper, 2017). "The volume of saliva was insufficient for analysis of both CgA epitopes in the dogs with traumatic bone fractures, and saliva CST could only be analyzed in 12 of the samples from healthy dogs." (PMID 28327184, 2017).
colon adenocarcinoma (1 paper, 2022). "Using different algorithms, we indicated that the infiltration of macrophages and M2 macrophages was positively associated with the gene expression of CgA (NED marker) in colon adenocarcinoma (COAD) and most rectal adenocarcinoma (READ)." (PMID 36030223, 2022). "According to the bioinformatics analysis in this study, the infiltration of macrophages, especially M2 macrophages, positively correlates with CgA and CXCR3 gene expression, respectively, in colon adenocarcinoma." (PMID 36030223, 2022).
colorectal NETs (1 paper, 2018). "•The associationof GIST and NET is difficult to suspect Serum CgA remains the most important biochemical marker in the diagnostics, monitoring, and establishing the prognosis in colorectal NETs." (PMID 30408742, 2018). "In fact, serum CgA remains the most significative biochemical marker in the diagnosis, monitoring and prognosis of colorectal NETs." (PMID 30408742, 2018).
congenital hemangioma (1 paper, 2022). A hemangioma present and fully formed at birth. "Of interest, CgA was detectable at very low levels in involutive IHs and congenital hemangiomas." (PMID 35563552, 2022).
Constipation (1 paper, 2017). Infrequent or difficult evacuation of feces. "The densities of Msi-1, NEUROG3, CgA, and serotonin cells were reduced in all IBS patients and in patients with diarrhea-predominant IBS (IBS-D), mixed-diarrhea-and-constipation IBS (IBS-M), and constipation-predominant (IBS-C) relative to the control subjects." (PMID 28764761, 2017).
COVID-19 (1 paper, 2022). A disease caused by infection with severe acute respiratory syndrome coronavirus 2. "Patients who died had higher plasma levels of CgA at admission than COVID-19 survivors (0.948 [0.514–1.754] nM vs 0.507 [0.343–0.785] nM respectively, p = 0.00026)." (PMID 35468164, 2022). "This study provides the first evidence of an elevation of CgA and its fragment VS-I in COVID-19 patients suggesting a neuroendocrine activation in these patients." (PMID 35468164, 2022). "We found that in COVID-19 patients the extent of CgA release into the blood predicts clinical outcome." (PMID 35468164, 2022). "The observation that CgA accumulates in patients with COVID-19 and that this occurs preferentially in those that eventually die offers a tool to disentangle the immune/neuroendocrine connection in the host response to SARS-CoV-2." (PMID 35468164, 2022). "Plasma CgA levels increase in COVID-19 patients and represent an early independent predictor of mortality." (PMID 35468164, 2022). "The aims of this study were to assess whether the release of CgA and VS-I in circulation is part of the early host response in COVID-19 and whether these molecules, measured at disease onset, might predict adverse outcomes." (PMID 35468164, 2022). "Thus, CgA accumulation in patients with severe COVID-19 might affect the microvascular response to the SARS-CoV-2 infection, possibly influencing the clinical outcome." (PMID 35468164, 2022). "We did not identify the origin and mechanisms of CgA production in COVID-19 patients." (PMID 35468164, 2022). "In contrast, the proteolytic processing of CgA yielding VS-I did not change in patients with severe outcome, suggesting that the molecular machinery involved in the generation of VS-I is similarly regulated in COVID-19 patients regardless of disease progression." (PMID 35468164, 2022).
dental caries (1 paper, 2022). The decay of a tooth, in which it becomes softened, discolored, and/or porous. "The dental caries experience ratio was significantly higher in the stress group, and only the concentration of CgA, a salivary stress protein, showed a significant difference." (PMID 36475120, 2022).
dependent (1 paper, 2013). "The reduction in abundances, plasma CgA, and tumour number and size by netazepide show that type 1 NETs are gastrin-dependent tumours." (PMID 24098507, 2013).
diabetic nephropathy (1 paper, 2022). "In this study, we aimed to estimate serum CgA levels and to evaluate the role of serum CgA in the early diagnosis of diabetic nephropathy (DN)." (PMID 35062888, 2022).
diabetic retinopathy (1 paper, 2021). "Patients with diabetic retinopathy have higher levels of CgA, CgB, and CgC in the vitreous humor." (PMID 34204153, 2021). "The levels of CgA, CgB, and CgC in the vitreous humor are higher in patients with diabetic retinopathy compared with nondiabetic subjects." (PMID 34204153, 2021).